IL6 (interleukin 6)
Diseases named in the same sentence as IL6 in open-access papers (continued):
Sharing a sentence is not in itself a finding about the gene and the disease.
gout (continued). "Several studies have focused on the relationship between gout and candidate inflammatory genes including IL-1β, IL-6, IL-8, IL-18, and TNF-α, however, the disease pathogenesis is still not fully understood." (PMID 26890073, 2016). "In patients with gout, the pro-inflammatory cytokines such as IL-1β, IL-6 and TNF-α can reduce the synthesis and secretion of apolipoprotein in hepatocytes by affecting HMG-CoA reductase, leading to reduced levels of lipids and lipoprotein levels." (PMID 24068523, 2014). "In general, patients with a history of gout had a less favourable cardiometabolic risk profile, for example median hs-CRP was 5.0 mg/L, IL-6 was 3.8 pg/mL, and mean serum uric acid level was 6.9 mg/dL." (PMID 23029307, 2012). "A comparison of patients with RA, OA, psoriatic arthritis and gout recorded the highest levels of IL-1β, IL-6, IL-8 and IDO as well as the lowest levels of tryptophan in RA synovial fluids, indicating stimulated cellular immune responses in RA patients." (PMID 16277684, 2005). "Furthermore, the 2-h human blood ex vivo gout inflammation model showed significantly elevated levels of IL-1β, IL-6, JAK2 mRNA, and their respective proteins, including phosphorylated JAK2 and STAT1/3, compared to both control groups." (PMID 40170729, 2025). "Previous studies have exhibited that honeysuckle polysaccharides could exert anti-gout activity by downregulating the levels of inflammatory factors IL-1β, IL-6, and TNF-α in the serum of mice in a sodium urate-induced gouty arthritis model." (PMID 40942068, 2025). "Studies have shown that the absence of HDAC3 in macrophages alleviates MSU crystal-induced gout inflammation by inhibiting the TLR2/4-driven IL-6/STAT3 signaling pathway, suggesting that HDAC3 may serve as a potential therapeutic target for gout." (PMID 41311848, 2025). "This strategy could lead to novel therapeutic methods or drugs that target the IL-6 signaling pathway in gout management." (PMID 40170729, 2025). "Additionally, in the MSU-induced human blood ex vivo gout model over 0–12 h, IL-1β and IL-6 protein expression levels increased at 1 h and peaked between 4 and 6 h compared to baseline." (PMID 40170729, 2025). "Additionally, the levels of IL-6 protein and JAK2 mRNA were positively correlated with certain inflammatory markers, reflecting their association with gout’s clinical and laboratory activities." (PMID 40170729, 2025). "Furthermore, Compared to 12-hour gout model WT mice, IL-1β, IL-6, JAK2, STAT1/3 mRNA, protein expression, and phosphorylated protein levels were notably decreased in IL-6 KO mice." (PMID 40170729, 2025). "Compared to baseline (0 h), both IL-1β and IL-6 protein levels were significantly elevated after 1 h (both P < 0.05), with peak inflammation observed at 4–6 h, indicating successful establishment of the acute gout inflammation model." (PMID 40170729, 2025). "However, the role and impact of IL-6 as an upstream regulator of the JAK2-STAT1/3 pathway in gout have seldom been reported." (PMID 40170729, 2025). "Mice with gout model supplemented with butyrate showed significant reductions in the foot thickness ratio and the levels of inflammatory factors (IL-1β, IL-6, and TNF-α) in their foot tissue." (PMID 39907694, 2025). "To determine whether IL-6 agonists exacerbate gouty arthritis via the JAK2-STAT1/3 signaling pathway, we conducted in vitro experiments." (PMID 40170729, 2025). "Overall, targeting IL-6 signaling could be an effective therapeutic strategy for treating gout or managing gout attacks." (PMID 40170729, 2025). "In gout, elevated IL-6 levels may serve as a marker for active IL-1β, as the ability of IL-1β to induce IL-6 is well-established." (PMID 41415576, 2025). "In addition, poor SARS-CoV-2 outcomes in patients with gout have been associated with increased serum levels of tumor necrosis factor a (TNF-a), interleukin-6 (IL-6) and interleukin-8 (IL-8)." (PMID 38686242, 2024).
gout (continued). "Another study indicated that oxidative stress and inflammatory markers including tumor necrosis factor, CRP, interleukin (IL) 1β, IL-6 may affect the development and clinical manifestations of gout based on hierarchical cluster analysis." (PMID 38678252, 2024). "Additionally, gout patients had significantly higher cytokines levels (including IL-2, IL-4, IL-6, IL-10, IL-17, IFN-γ, and TNF-α) than HCs; IL-2 levels were positively correlated with Treg cells and negatively correlated with ESR." (PMID 38240927, 2024). "Physical activity may exert anti-inflammatory effects by lowering IL-6, reducing C-reactive protein, and inhibiting TNF-α, thereby reducing the risk of gout." (PMID 38276301, 2024). "The IL-1 signaling member IL-18 and its receptor IL-18R1 and the IL-6 family of cytokines members IL-6, LIF-R, and OSM were also elevated in AH, which is in line with major studies implicating IL-1-driven inflammation and IL-6 signaling in the pathogenesis of gout." (PMID 37810213, 2023). "Regarding the inflammatory indicators, there was a significant increase in the levels of CRP (38.12 ± 48.46 vs. 7.55 ± 9.82, p = 0.014), IL-1β (55.92 ± 45.54 vs. 41.86 ± 32.42, p = 0.028) and IL-6 (45.89 ± 96.51 vs. 8.75 ± 6.43, p = 0.031) when the patient had an acute gout flare." (PMID 36896178, 2023). "In addition, our experiments showed that Simiao powder certainly regulates the expression of PPAR-γ, PTGS1, IL-6 and Bcl2 mRNA in ankle tissue in hyperuricemic-gout mice." (PMID 35672755, 2022). "Furthermore, Simiao powder certainly regulates the expression of PPAR-γ, PTGS1, IL-6 and Bcl2 mRNA in ankle tissue in hyperuricemic-gout mice." (PMID 35672755, 2022). "Previous studies have shown that IL-6, IL-1β, and TNF-α were associated with inflammatory activity in patients with gout." (PMID 35145506, 2022). "IL-6 acts mostly as a proinflammatory cytokine involved in the pathogenesis of gout, and may be a reliable prognostic marker for patients with gout." (PMID 36438835, 2022). "Meanwhile, gout is an autoinflammatory disease activated through the proinflammatory IL-6 cytokine." (PMID 33921811, 2021). "Moreover, IL-6 is a very important cytokine in inflammation, especially active in acute gouty arthritis, which can participate in the early activation of T-cell." (PMID 33442381, 2020). "The same study showed that synovial fluid from patients with gout exhibits high levels of IL-6." (PMID 30914954, 2019). "Immunologically, the T-cell pathway associated with interleukin-6, interleukin-8, and tumor necrosis factor is enhanced in patients with gout, irrespective of acute or chronic status." (PMID 30634389, 2019). "Besides, the inflammatory cytokine IL-6 was also inhibited by IL-33 treatment in the gout animal model." (PMID 30863362, 2019). "Although the properties of IL-6 during an acute-phase response are well known, the role of IL-6 in gout remains unclear." (PMID 30075804, 2018). "In mice, IL-6 is decreased by genetic and pharmacologic inhibition of IL-1 in gouty arthritis." (PMID 30075804, 2018). "It is likely that the increase in IL-6 in gout is a biomarker for active IL-1β." (PMID 30075804, 2018). "In addition, IL-1β can induce the expression of a wide range of cytokines and chemokines like TNF-α, IL-6, IL-17, and MCP-1 that are directly responsible for the influx of neutrophils into the synovium, a hallmark of gouty arthritis." (PMID 26709520, 2015). "RA and gout samples were matched in terms of macrophage numbers and IL-6 and IL-8 expression." (PMID 24314260, 2013).
gout (continued). "Consequently, we hypothesize that the IL-6-mediated JAK2-STAT1/3 pathway contributes to the progression of gout, possibly enhancing TLRs-mediated mechanisms." (PMID 40170729, 2025). "This suggests that heterozygous IL-6 KO mice may have been utilized to generate the gout model." (PMID 40170729, 2025). "It is likely that IL-6-mediated signaling may also contribute to gout pain." (PMID 38627393, 2024). "Therefore, therapeutic regimens targeting IL-6 inhibition attenuate the inflammatory response, thereby restoring Th17/Treg balance, which may be critical in the treatment of early-onset gout." (PMID 38240927, 2024). "Therefore, the enhanced TRPA1 channel functional activity we observed may be due to channel expression upregulation mediated by IL-1β, IL-6 or other inflammatory mediators released during gout." (PMID 33204337, 2020). "In GA patients, mRNA expression of IL-6, JAK2, STAT1/3, and IL-1β was notably lower in the gout group compared to the healthy control (HC) group." (PMID 40170729, 2025). "In a gout model using THP-1 cells treated with MSU at different time points, varying degrees of upregulation in IL-1β and IL-6 proteins were observed over time." (PMID 40170729, 2025). "IL‐6 activates STAT3 to promote neutrophil infiltration and joint inflammation, while SOCS3, a negative regulator of STAT3, is upregulated during gout flares, potentially mitigating inflammation by suppressing STAT3 signaling." (PMID 40613560, 2025). "The combined trends of IL-1β and IL-6 suggest that IL-6 gene knockout attenuates the JAK2-STAT1/3 signaling pathway, inhibiting pro-inflammatory cytokine production and alleviating MSU-induced gouty arthritis." (PMID 40170729, 2025). "Literature reviews, coupled with network pharmacology and bioinformatics predictions, have identified IL-6 and STAT1/3 as critical targets for anti-gout treatment." (PMID 40170729, 2025). "Elevated serum levels of TNF-α, IL-6, and IL-1β are commonly observed in HUA and gout patients, reflecting inflammasome activation and immune dysregulation." (PMID 40870677, 2025). "This suggests a crucial role for phosphorylated proteins in gout’s inflammatory response and indicates involvement of the IL-6 and JAK2-STAT1/3 signaling pathways in gout pathogenesis." (PMID 40170729, 2025). "The expression levels of IL-1β, IL-6, JAK2, and STAT1/3 mRNA were significantly lower in the gout group compared to the HC group (all P < 0.001)." (PMID 40170729, 2025). "In the 2h human blood in vitro gout inflammation model, expressions of IL-1β, IL-6, JAK2 mRNA, and IL-1β, IL-6, JAK2, STAT1/3, p-JAK2, p-STAT1/3 proteins were significantly higher compared to both the blank control and PBS-negative control groups." (PMID 40170729, 2025). "These novel biomarkers of XOI treatment effects were identified within an interactome with central gout mediators including IL-1B, CXCL8, IL6, and C5." (PMID 39426967, 2024). "During gout flare-ups, the JAK2/STAT3 signaling pathway is activated, leading to increased expression of cytokines such as IL-6, IL-1β, and TNF-α in both the kidneys and joints." (PMID 39611154, 2024). "The target genes of Terpine-4-ol, a main compound of ZP, were overlapped with the gouty arthritis-related genes such as NLRP3, PTGS2, CXCL8, IL6, TNF, IL1B, TLR4, and ALB." (PMID 39861092, 2024). "In a rat gouty arthritis model established by injecting MSU crystals, LJP-1 ameliorated the degree of ankle swelling in rats and decreased the IL-1β, IL-6, TNF-α, and cyclooxygenase-2 (COX-2) levels in the serum, eventually alleviating gouty arthritis." (PMID 37375383, 2023). "Plasma levels of pro-inflammatory cytokines IL-1β, IL-6, IL-12p70 and TNF were elevated in RA patients in contrast to OA and gout, with significant differences between RA and OA groups (p < 0.05)." (PMID 37202736, 2023).
gout (continued). "During gout flare-ups, the activation of JAK2/STAT3 signaling results in an elevation of cytokine expression, including IL-6, IL-1β, and TNF-α, within the kidneys and joints." (PMID 38094893, 2023). "We found that dsDNA expression increased during gout remission, while IL-1β, MCP-1, TNF and IL-6 levels decreased significantly." (PMID 37810893, 2023). "Febuxostat is a drug used for the treatment of gout that has anti-inflammatory properties, by inhibiting TNF-α and IL6, along with antioxidant and antifibrotic roles." (PMID 37763811, 2023). "Subsequently, neutrophils extracted from patients with gouty arthritis were induced to form NETs by MSU crystals and added to the medium containing IL-1β, MCP-1, TNF and IL-6." (PMID 37810893, 2023). "Research demonstrated that multiple pro-inflammatory cytokines, such as IL-6 and TNF-α, are related to gouty arthritis." (PMID 34586567, 2022). "When the quail showed gout symptoms, the NLRP3 inflammasome was activated, and the expressions of IL-1β, TNF-α, IL-6, IL-8, and IL-18 were significantly increased." (PMID 36569836, 2022). "In turn, neutrophils interact with MSU crystals and induce the release of IL-1, IL-6, TNF-α, and other cytokines, resulting in pain and erythema related to gout flare." (PMID 34586567, 2022). "In our study, high levels of IL-1β, IL-6 and TNF-α were observed in LPS and MSU induced gout in THP-1 cells, which means gout model in vitro was successful." (PMID 35462936, 2022). "In this study, we found that IL-1β, TNF-α, and IL-6 were significantly increased in synovial tissues and serum of MSU-induced rat gout models, which is consistent with the characteristics of the GA inflammatory reaction." (PMID 32774151, 2020). "These inflammatory cytokines (IL-6, IL-8, IL-1β, and TNF-α) exert differential effects on vascular inflammation and dysfunction in patients with gout, a condition characterized by hyperuricemia." (PMID 33330657, 2020). "Nonetheless, we found higher plasma levels of IL-1β, IL-1ra, IL-4, IL-6, IL-8, IL-9, IL-13, IL-17, FGF-basic, IFNγ, and TNFα in acute gouty arthritis patients." (PMID 31739430, 2019). "The ACP inflammatory cytokine profile was similar to that seen in gout, specifically regarding the high levels of IL1B, IL6 and IL18." (PMID 29541918, 2018). "For example, gout comorbidities and systemic inflammation with expression of pro-atherogenic cytokines IL-1β, IL-8/CXCL8, and IL-6 have the capacity to accelerate atherogenesis." (PMID 28818081, 2017). "In summary, the concentrations of ox-LDL and pro-inflammatory cytokines IL-1β, IL-6 and TNF-α significantly increased in gout patients in our study, while TGF-β concentrations significantly decreased in gout patients relative to controls." (PMID 24068523, 2014). "The production of IL-6 by MSU/C18:0 was in line with IL-1β production in cells isolated from gout patients, with a trend towards higher cytokine production in gout patients than in healthy controls." (PMID 22762240, 2012). "This study explores the influence and role of upstream IL-6 in regulating the JAK2-STAT1/3 signaling pathway on gout inflammation, offering new insights for targeted therapeutic interventions and drug development in gout management." (PMID 40170729, 2025). "To explore whether IL-6 KO alleviates gouty arthritis through the JAK2-STAT1/3 pathway, and to confirm the role of IL-6 KO in the inflammatory response induced by MSU crystals, we conducted in vivo experiments in mice." (PMID 40170729, 2025). "Moreover, IL-6, JAK2, STAT1/3, p-JAK2, p-STAT1/3, and IL-1β proteins were markedly higher in the acute gout (AG) group compared to the intercritical gout (IG) and HC groups." (PMID 40170729, 2025). "Deficiency of HDAC3 in macrophage alleviates MSU crystals-induced gouty inflammation through inhibition of TLR2/4 driven IL-6/STAT3 signaling pathway, suggesting that HDAC3 could contribute to a potential therapeutic target of gout." (PMID 38711064, 2024).
gout (continued). "For example, targeting the JAK2/STAT3 signaling pathway could reduce the expression of pro-inflammatory cytokines like IL-6, IL-1β, and TNF-α, thereby alleviating gout symptoms and slowing disease progression." (PMID 39611154, 2024). "Then, we compared cytokine levels, including IFN-γ, TNF-α, IL-2, IL-4, IL-6, IL-10 and IL-17 among gout with tophus, gout without tophus and HCs." (PMID 38240927, 2024). "In addition, both male and female particip ants treated for gout had higher baseline ASCVD scores and higher baseline IL-6 levels." (PMID 40787635, 2023). "Six significantly distinct proteins were identified in the serum proteomic profile of gout flares, these patients having elevated circulating concentrations of MMP-1, IL-6, VEGFA, and CCL23 and decreased DNER (Delta and Notch-like epidermal growth factor-related receptor) and CD6 levels." (PMID 37810213, 2023). "In addition, we divided the onset of gouty arthritis into acute and remission stages and then assessed the expression of serum dsDNA, IL-1β, MCP-1, TNF and IL-6." (PMID 37810893, 2023). "Nominally significant differences were observed for 7 proteins: TRAIL (TNF-related apoptosis-inducing ligand), DNER, IL-10, and CCL3 were reduced, and IL-6, RANKL (Receptor activator of nuclear factor kappa-Β ligand), and MCP-3 were elevated in samples of patients with tophaceous gout." (PMID 37810213, 2023). "In our study, injection of MSU crystals and feeding with HFD caused a decrease in the relative abundance of Bacteroides, which was significantly negatively correlated with the levels of UA, IL-1β, IL-6, TNF-α, MPO activity, and purine and pyrimidine metabolisms in mice with gout." (PMID 35145506, 2022). "Dapansutrile may reduce the expression of MMP3 by regulating IL6, IL18, and IL17A, thereby degrading the extracellular matrix to deal with gouty arthritis." (PMID 36105284, 2022). "Considering the important effect of pro-inflammatory cytokines on the development of acute gouty arthritis, we explored whether GPS could inhibit the release of IL-1β, IL-6, IL-18, and TNF-α." (PMID 34586567, 2022). "In addition, the main characteristic chemical components of Simiao Powder have good binding ability with IL-6, PTGS1, PPARG and BCL2 targets, which indicates that the active components of Simiao Powder can effectively treat gout by combining with core targets." (PMID 35672755, 2022). "Dapansutrile may regulate extracellular matrix degradation by reducing MMP3 expression through IL6, IL18, and IL17A in the treatment of gouty arthritis." (PMID 36105284, 2022). "In this study, similar results were revealed showing the decreased relative abundance of Lachnospiraceae and the significantly negative correlation between the relative abundance of Lachnospiraceae and the levels of UA, IL-1β, IL-6, TNF-α, MPO activity, and purine metabolism in mice with gout." (PMID 35145506, 2022). "A recent randomized, double-blind, placebo-controlled pilot study showed a positive correlation between UA serum levels and IL-6, IL-17, and TNF-α, suggesting that xanthine oxidase inhibitors reduce levels of serum UA but also of these cytokines in patients with gout." (PMID 35237183, 2021). "As a result, various cytokines and chemokines are released, and in particular, IL-1β and TNF-α promote the recruitment of neutrophils, resulting in the inflammation of gouty arthritis through the release of a large amount of proinflammatory substances such as IL-1β, TNF-α, and IL-6." (PMID 34564665, 2021). "In addition, JGT efficiently downregulated MSU crystal-induced swelling and pain and contrasted inflammation by suppressing pro-inflammatory cytokines (IL-1β, TNF-α, and IL-6) and MPO activity in a gouty arthritis mouse model." (PMID 33371241, 2020).